MTOR (mechanistic target of rapamycin kinase)
Diseases named in the same sentence as MTOR in open-access papers (continued):
Sharing a sentence is not in itself a finding about the gene and the disease.
ovarian carcinoma (continued). "Conclusion: 1) MiR-8485 may be the key factor of BJOE in promoting autophagy and apoptosis and inhibiting cell proliferation of ovarian cancer cells; 2) BJOE may play an antitumor role by regulating LAMTOR3/mTOR/ATG13 signaling axis through miR-8485 to promote autophagy in ovarian cancer cells." (PMID 35959437, 2022). "Finally, considering that the PI3K/AKT/mTOR signaling pathway is commonly activated in ovarian cancer and plays an important role in the regulation of cell cycle and apoptosis, we attempted to explore the effect of UBE2S knockdown on the PI3K/AKT/mTOR signaling pathway." (PMID 35658829, 2022). "Indeed, a recent study in ovarian cancer suggested that a combination of the FGFR inhibitor infigratinib and the mTOR inhibitor rapamycin induced remarkable cell cycle arrest and apoptosis in ovarian cancer cells, and reduced tumor size in the xenograft animals after the treatment." (PMID 35326708, 2022). "Finally, MCP-1, which is produced by adipocytes, has been shown to induce migration and omental metastasis by binding to its cognate receptor CCR-2 on ovarian cancer cells and in turn activating the PI3K/AKT/mTOR pathway and its downstream effector HIF-1a and VEGF-A." (PMID 35565396, 2022). "In ovarian cancer, knockdown of HSP60 suppresses pathways related to OXPHOS and alters metabolic pathways to allow accumulation of adenine, which activates the adenine-AMPK pathway, suppresses the mammalian target of rapamycin (mTOR) pathway, and inhibits cancer progression." (PMID 35864539, 2022). "However, the role of BI853520 in regulating PI3K/AKT/mTOR pathway of ovarian cancer cells has not yet been reported." (PMID 35201437, 2021). "The mTOR pathway is a central regulator of cellular events such as proliferation, apoptosis and angiogenesis gauging external energy, growth factor and stress signals with the PI3K/AKT/mTOR pathway being a highly activated cellular signalling pathway in advanced ovarian cancer." (PMID 34062972, 2021). "Finally, there also appears to be cross-talk between DYRK1B and the mammalian target of rapamycin (mTOR) pathway, with DYRK1B expression upregulated upon mTOR inhibition and mTOR/AKT activation induced by DYRK1B within the Hh signaling pathway in pancreatic and ovarian cancer cells." (PMID 32751160, 2020). "In ovarian cancer, BEZ235 significantly prevents hypoxia- and TGF-β1-induced EMT and up-regulates the E-cadherin expression in vitro and in vivo, suggesting that dual inhibition of AKT and mTOR may have the potential for treatment of cancer metastasis." (PMID 33659215, 2020). "Based on the proteomic and viability investigation, metformin may involve the alternation of phosphorylation in the AKT/mTOR pathway accompanying cell retardation in ovarian cancer, without affecting the total amount of protein." (PMID 32825834, 2020). "Therefore, inhibiting Akt/mTOR, as well as inhibiting PKM2, by MHY2245 treatment can increase autophagy, which may enhance antitumor effects of MHY2245 in ovarian cancer cells." (PMID 32398958, 2020). "However, addition of enzalutamide, the AR inhibitor, to the ovarian cancer cells did not increase levels of phospho-mTOR (Figure." (PMID 34926721, 2019). "Importantly, we are the first to demonstrate that TAK1/NF-κB signaling, as the dominant downstream signaling pathway, is similar to mTOR signaling, inversely modulated by AMPK activity, and involved in ovarian cancer aggressiveness in the intraperitoneal cavity or ascites microenvironment." (PMID 31372520, 2019). "Continuing from these mechanistic findings, we could furthermore demonstrate that a pharmacological therapy combining the targeted inhibition of DYRK1B with that of PI3K/mTOR/AKT has strong effects on Hh/GLI signaling and on cell growth of DYRK1B-amplified pancreatic and ovarian cancer cells." (PMID 27903983, 2017).
ovarian carcinoma (continued). "In summary, this study demonstrates, for the first time, the reversal MDR potential of GFW for ovarian cancer in vitro and in vivo by inhibiting the protein expression and function of P-gp, which may act through the inactivation of the PI3K/AKT/mTOR signalling pathway." (PMID 27293459, 2016). "In ovarian cancer cell lines, E2 has been found to stimulate telomerase activity via two mechanisms – transcriptional regulation of hTERT via an ERE-dependent mechanism and the PI3K/Akt/mTOR cascade as well as post-translational regulation through Akt-dependent phosphorylation of hTERT." (PMID 23409030, 2013). "Moreover, NAC pretreatment reversed the downregulation of the anti-apoptotic proteins p-AKT, p-mTOR, NF-κB, BCL-2, BCL-xL, c-IAP1 and survivin, suggesting that ROS play a key role in mediating the antiproliferative and apoptosis-inducing effects of bardoxolone methyl in ovarian cancer cells." (PMID 40732256, 2025). "Hence, we speculate that CAFs may secrete extracellular vesicles or exosomes containing miR-1290 and OGN, thereby affecting the expression of E-cadherin, mTOR and AKT in ovarian cancer cells and mediating the proliferation and metastasis of ovarian cancer cells." (PMID 38402185, 2024). "Knockdown of UBE2S could block the cell cycle and promote apoptosis by inhibiting the PI3K/AKT/mTOR pathway and ultimately inhibit the proliferation, migration and prognosis of ovarian cancer, which suggested that UBE2S might be used for molecular therapy and prognostic evaluation of ovarian cancer." (PMID 35658829, 2022). "Moreover, the results on dual DYRK1B-PI3K/AKT/mTOR/S6K inhibition were not specific to Panc1 cells as we could reproduce them in Ovcar-3 ovarian cancer cells using combinations of AZ191 and inhibitors targeting PI3K, mTOR, AKT and S6K." (PMID 27903983, 2017). "However, it was not clear whether NC affected ovarian cancer cells through Akt/mTOR pathway." (PMID 37317923, 2023). "Knockdown of CirSLC7A6 alone did not improve the cisplatin sensitivity of ovarian cancer cells, despite inactivation of the PI3K/Akt/mTOR and Erk/p38 MAPK pathways." (PMID 37940982, 2023). "Last but not least, FAM83D can also promote ovarian carcinoma cell invasion and proliferation, while suppressing autophagy through the PI3K/AKT/mTOR signaling pathway." (PMID 35489022, 2022). "Although in ovarian cancer the key relationship between miR-100 and the mTOR pathway was confirmed, in our RCC model the tendency to increase miR-100-5p after PTEN knockout was not sufficient to change mTOR expression." (PMID 35625614, 2022). "As single agent therapies, the efficacy of PI3K/AKT/mTOR inhibitors in the treatment of a variety of cancers has generally not been satisfactory and phase III clinical trials have not been reported yet in patients with ovarian cancer." (PMID 31547471, 2019). "Our findings suggest that a diet high in plant protein reduces the growth of human ovarian cancer cells in mice compared to a diet high in animal protein, ―possibly through the lack of activation of the IGF/Akt/mTOR pathway, and leads to a better prognosis with or without cisplatin treatment." (PMID 29844867, 2018). "Moreover, the reduced viability of ER-positive and -negative cancer cell lines treated with FVE through inactivation of the PI3K/Akt/mTOR pathway suggests that FVE may be useful in the treatment of some breast, endometrial and ovarian cancers regardless of ER status." (PMID 27234961, 2016). "Additionally, the overexpression of PBK failed to promote ovarian cancer cell autophagy with mTOR or ERK1/2 knockdown, and the restoration of mTOR or ERK1/2 expression could partly rescue the autophagy blocked by knockdown of mTOR or ERK1/2 in A2780 and SKOV3 cells." (PMID 30778048, 2019).
melanoma (639 papers, 2005 to 2026). A malignant, usually aggressive tumor composed of atypical, neoplastic melanocytes. "One of the key pathways implicated in melanoma progression is the PI3K/AKT/mTOR signaling cascade, which plays a central role in regulating cell growth, proliferation, invasion, apoptosis, autophagy, and metabolic reprogramming." (PMID 40869090, 2025). "In malignancies like liver and colorectal cancer, dysregulated activation of the PI3K/Akt/mTOR signaling pathway has been implicated in melanoma progression." (PMID 39844566, 2025). "The observed decrease in phosphorylation levels of BRAF, PI3K, AKT1, and mTOR is particularly relevant, as constitutive activation of these pathways has been strongly associated with melanoma growth and resistance to therapy." (PMID 40806647, 2025). "The dysregulation of PI3K/Akt/mTOR signaling is often observed in melanoma due to genetic alterations, such as mutations and amplifications in pathway components." (PMID 39200315, 2024). "Accumulated evidence indicates that activation of the mTOR pathway is strongly associated with the pathogenesis of melanoma." (PMID 38334632, 2024). "Of note, compared to chronic sun-damaged melanoma (6.7%), mTOR mutations were more common in AM (11.0%)." (PMID 38469235, 2024). "Both PI3K/AKT/NF-κB and PI3K/AKT/mTOR are the two main mutated pathways involved in apoptosis and tumorigenesis facilitating the development of melanoma resistance to anti-cancer agents." (PMID 38334632, 2024). "In preclinical studies, Dnmt3b deficiency was shown to prevent melanoma development in Braf- and Pten-deficient murine melanocytes through modulation of the mTOR pathway." (PMID 37160317, 2023). "Nonsynonymous mTOR mutations are present in 10.4% (N=412) of melanoma patients and are associated with a poor prognosis." (PMID 35402264, 2022). "The rate of nonsynonymous mTOR mutations was approximately 10% in malignant melanoma patients, and nonsynonymous mTOR mutations were connected to a poor prognosis." (PMID 36539659, 2022). "This transition from primary melanoma to metastatic type has been associated with Akt activation, acting as a link between signals and mTOR/S6K1 upregulation, while enhancing angiogenesis, which further nurtures the aggressiveness of metastatic melanomas." (PMID 35163615, 2022). "Activation of the signaling pathway mTOR (mammalian target of rapamycin), a serine/threonine kinase, has been strongly associated with the development of different neoplasms, including melanoma." (PMID 36686160, 2022). "MTOR mutations are common in malignant tumors, such as endometrial carcinoma, melanoma, esophagogastric adenocarcinoma, colorectal adenocarcinoma, renal cell carcinoma, and bladder cancer." (PMID 35402264, 2022). "EGCG binding to 67LR elicits activation of PP2A via the adenylate cyclase (AC)/cyclic adenosine monophosphate (cAMP) axis, causing melanoma-specific mammalian target of rapamycin (mTOR) inhibition and merlin activation related to tumor suppression." (PMID 36014370, 2022). "Primary benign and malignant melanomas progress to invasive stage rapidly, while this transition from primary to more aggressive invasive melanomas and metastatic forms has been associated with Akt/mTOR activation." (PMID 35163615, 2022). "Other candidates harbored identical rare variants within the TCGA kidney and/or melanoma series, such as MTOR." (PMID 34067022, 2021). "Strikingly, in melanoma PTEN loss results in constitutive PI3K/mTOR pathway activation, which leads to ICB resistance via induction of VEGF." (PMID 33922556, 2021). "The network defined by phosphatidylinositol-3-kinase (PI3K), AKT, and mammalian target of rapamycin (mTOR) plays a major role in melanoma oncogenesis and has been implicated in BRAF inhibitor resistance." (PMID 34680615, 2021). "Further rationale for targeting mTOR comes from recent findings that activating mutations in mTOR are relatively common in melanoma, something we also observe." (PMID 33549048, 2021).
melanoma (continued). "Overall, most BRAFi resistant melanomas have reactivated the MAPK pathway or upregulated the PI3K/AKT/mTOR pathway through specific mutations." (PMID 34066966, 2021). "We investigated the effect of everolimus (mTOR inhibitor) on the signaling pathway associated with the mTORC1 and mTORC2 complexes in melanoma Lu1205 and WM793 cell lines." (PMID 31586300, 2020). "Several mechanisms can activate PI3K/AKT/mTOR signaling in melanoma, including the loss of tumor suppressor PTEN functions, mutations in AKT and PIK3CA, and compensatory signaling through growth factor receptors." (PMID 32528879, 2020). "Treatment of melanoma cells with 5 nM everolimus resulted in the decrease of the level of phosphorylated mTOR protein (Ser2448)—associated with the complex mTORC1—by 80% in the case of the Lu1205 line, and by 60% in the WM793 line." (PMID 31586300, 2020). "We, therefore, analyzed the mTOR response using immunofluorescence in a different human melanoma cell line bearing the BRAF V600E mutation (G361)." (PMID 32531927, 2020). "Using melanoma models, we recently reported that Akt acts as a molecular switch linked with elevated mTOR, S6K1, angiogenesis, and concomitant production of peroxides, which further nurture the aggressiveness of metastatic melanoma." (PMID 31370278, 2019). "Fisetin has been investigated for treatment cutaneous cancer, particularly melanoma, having constitutive activation of the Akt/mTOR signaling, due to mutations of PTEN, PIK3CA, or TSC1/2." (PMID 31370278, 2019). "Activation of the mTOR pathway has been suggested to be strongly associated with the pathogenesis of melanoma." (PMID 31370278, 2019). "A recent study, composed of 412 melanoma samples, has shown that 10.4% of these melanoma cases presented somatic MTOR mutations." (PMID 30166456, 2018). "Recent research suggests that mTOR mutations often occur in melanoma patients and are of worse therapeutic prognosis." (PMID 29214525, 2017). "Our results are in line with these observations in that we found that cryptolepine treatment induced activation of AMPKα1/2 in melanoma cells and caused inhibition of the protein synthesis machinery by reducing the phosphorylation of mTOR, p70S6K and 4E-BP1." (PMID 28473727, 2017). "Compared to co-targeting of mutant BRAF and PI3K/mTOR, the association of a MEK1/2 and a PI3K/mTOR inhibitor was more effective in the activation of Bax and of caspase-3 and in the induction of caspase-dependent melanoma apoptosis." (PMID 26678033, 2016). "Taken together, these results indicated that intrinsic resistance to BRAFV600E inhibition can be frequently associated with cross-resistance to MEK1/2 and/or PI3K/mTOR inhibitors in BRAF-mutant melanoma cells." (PMID 26678033, 2016). "In the present investigation, we found that fisetin inhibited expression of PI3K and enhanced expression of PTEN as well as decreased phosphorylation of AKT and mTOR in BRAF-mutated melanoma cells." (PMID 26299806, 2015). "It is also plausible that the oncogenic function of NRF2 in melanoma cell lines drives high basal ROS and hyperactive mTOR signaling, which has been shown to result from NRF2 mutations." (PMID 25749517, 2015). "Aberrant activation of the PI3K/Akt/mTOR pathway has been associated to the development of many malignant diseases, including melanoma, as a consequence of deregulation of one or more molecules involved in this pathway." (PMID 24920406, 2014). "Previous studies have shown that mTOR is highly activated in the majority of melanoma cases and is associated with poorer prognosis characteristics of the disease." (PMID 24913145, 2014). "The PI3K/AKT/mTOR pathway is dysregulated in many types of cancer, including melanoma, and is associated with poor prognosis." (PMID 23383069, 2013).
melanoma (continued). "In the absence of the autophagy inhibitor HCQ, CCI-779 caused cytostatic growth arrest and autophagy induction in melanoma cell lines, both of which contributed to the sustained survival of these cells with mTOR inhibition alone." (PMID 23383069, 2013). "Overall, these two papers further validated the mutated B-Raf/MEK/ERK and the PI3K/Akt/mTOR pathways, as promising therapeutic targets in melanoma." (PMID 23006971, 2012). "Targeting both MEK and mTOR is a method to target melanoma which often have mutations at BRAF and increased activation of the PI3K/PTEN/Akt/mTORC1 pathway." (PMID 23455493, 2012). "Among the 31 significantly enriched pathways in the WT vs. HB comparison, those associated with high-altitude adaptation included mTOR signaling (oas04150), melanoma (oas05218), fatty acid metabolism (oas01212), Wnt signaling (oas04310), cancer (oas05200), and metabolic (oas01100)." (PMID 40895789, 2025). "Reduced ERK signaling in melanoma cells may cause hyperactivation of the PI3K/AKT/mTOR pathway, contributing to the development of acquired resistance to BRAFi." (PMID 40872623, 2025). "Based on the findings that the upregulation of DYRK3 in melanoma skin cancer cells and dysregulation of the mTOR pathway are closely associated with various types of human tumors, we investigated the effect of DYRK3-mediated activation of the mTORC1 pathway on melanoma cancer cell growth." (PMID 38519031, 2024). "These mutations in mTOR can be recognized as indicators of poor prognosis in melanoma." (PMID 38921444, 2024). "Mutations in mTOR (mammalian target of rapamycin) can also be present in melanoma." (PMID 38469235, 2024). "In addition to the frequent mutation to AKT family members, mutations to the PI3K/AKT/mTOR pathway are common in melanoma." (PMID 38334632, 2024). "PI3K-AKT-mTOR pathway inhibitors present a promising therapeutic option for patients with mTOR-mutated melanoma; non-synonymous mTOR mutations have been strongly linked to reduced survival in melanoma patients." (PMID 38469235, 2024). "Non-synonymous mTOR mutations were found in 10.4% of 412 melanomas." (PMID 38469235, 2024). "Enhanced glycolysis (Warburg effect) driven by the BRAF oncogene, dysregulated GAPDH expression, and activation of the PI3K/AKT/mTOR signaling pathway may significantly contribute to the resistance-targeted therapy of BRAF-mutated melanomas." (PMID 37895015, 2023). "Crizotinib may be used as a complementary therapy for melanoma with BRAF mutations by inhibiting the mTOR/Insulin signaling pathway." (PMID 37770477, 2023). "In a new phase II study of everolimus in patients with advanced melanoma characterized by mTOR mutations; the results revealed that patients with mTOR-mutated melanoma respond significantly better, whereas mTOR inhibitors have a limited effect in patients with unselected melanoma." (PMID 36428613, 2022). "Targeting metabolic pathways and the mTOR pathway may facilitate the development of new therapies to overcome Vem-resistance problems in BRAF mutated melanoma." (PMID 36034784, 2022). "Moreover, melanoma patients frequently display non-synonymous mutations of the MTOR gene, and such mutations can predict a worse prognosis." (PMID 35912100, 2022). "Furthermore, the inhibition of mTOR causes strong synergism with the BRAF inhibitor in BRAF inhibitor-resistant melanoma." (PMID 36014370, 2022). "Thus, the incubation of the keratinocytes with EVs derived from the metastatic melanoma cells activates the AKT/mTOR and ERK signaling pathways, which are implicated in the control of cell migration." (PMID 35327461, 2022). "Notably, mTOR mutations were more frequent in acral melanomas (11.0%) than in chronically sun-damaged melanomas (6.7%)." (PMID 34149718, 2021). "Nonsynonymous MTOR mutations are present in about 3.61–12% of melanoma patients." (PMID 32850962, 2020).